PDIA6 (protein disulfide isomerase family A member 6)
Diseases named in the same sentence as PDIA6 in open-access papers (continued):
Sharing a sentence is not in itself a finding about the gene and the disease.
cancer (24 papers, 2013 to 2026). A tumor composed of atypical neoplastic, often pleomorphic cells that invade other tissues. "PDIA6 plays a pivotal role in protein folding and ER stress regulation, and its dysregulation has been associated with cancer progression, including PDAC." (PMID 40719618, 2025). "A body of literature has uncovered that a high expression of PDIA6 was linked to development of cancers." (PMID 39741300, 2024). "Recent studies have reported that PDIA6 is implicated in the pathogenesis of human cancers." (PMID 34781823, 2021). "The second μ-17-specific cancer-associated module comprises endoplasmic reticulum (ER) molecular chaperones (PDIA4, PDIA6, GANAB) and heat shock proteins (HYOU1, HSPA5, DNAJB11)." (PMID 41373892, 2025). "Knockdown of PDIA6 has been shown to suppress cell proliferation, invasion, migration, and chemoresistance while enhancing apoptosis in cancer cells." (PMID 40719618, 2025). "Large number of studies have shown that PDIA6 is related to the development of a variety of cancers." (PMID 38097564, 2023). "And high expression level of PDIA1 and PDIA6 correlate with the resistance to common chemotherapy drugs in cancer cells." (PMID 36003400, 2022). "PDIA6 has an isomerase function and its overexpression has been correlated with a poor cancer prognosis and serves as a biomarker for non-small cell lung cancer (NSCLC)." (PMID 36761330, 2022). "For example, PDIA6 was upregulated in non-small cell lung cancer cells and inhibited apoptosis and autophagy of cancer cells." (PMID 34781823, 2021). "Microarray data analysis has demonstrated the upregulation of several typical PDI members including PDIA1, PDIA3, PDIA4 and PDIA6 in multiple cancers such as breast, colorectal, liver, brain and prostate." (PMID 33742523, 2021). "Likewise, other PDI members namely PDIA3, PDIA4, and PDIA6 are also highly expressed in numerous cancer types including breast, thyroid, rectal, gastric and liver cancers." (PMID 35965326, 2022). "PDI family proteins, such as AGR2, PDI, PDIA3, PDIA4, and PDIA6 are reportedly upregulated in cancers, which are correlated with cancer progression and metastatic disease in pancreatic, kidney renal clear cell carcinoma (KIRC), ovarian cancers, glioblastoma and lung adenocarcinoma." (PMID 36202782, 2022). "Up to now, PDIA6 has been verified to serve as an oncogene in several kinds of cancers." (PMID 33761940, 2021). "Likewise, the miR-376a target genes MYC, NRP1 (Neuropilin-1), and PDIA6 (Protein Disulfide Isomerase Family A Member 6) play crucial roles in cancer-related processes." (PMID 31847321, 2019). "ENO1, GAPDH, NQO1, PDIA4, and PDIA6 may serve as potential targets for cancer therapy." (PMID 37955007, 2023). "Recent studies have shown that several PDIs, such as PDIA1, PDIA3 and PDIA6, are upregulated in different cancer types, including kidney, lung, brain, ovarian, melanoma, prostate and male germ-cell tumours, and over-expression of PDIs may serve as a diagnostic marker for cancer." (PMID 33023153, 2020). "The differential expression of DDAH1 and PDIA6 in GSTP1 knockdown PDAC cells is particularly intriguing, as both are involved in redox homeostasis and are frequently upregulated in various cancers." (PMID 40719618, 2025). "However, it is unknown whether the effect of RBM47 on cancer cell metabolism is related to PDIA6." (PMID 39741300, 2024). "The expression of PDIA3, PDIA4, PDIA6, ERP29, and TXNDC5 have also upregulated in most cancer types." (PMID 35965326, 2022). "Regarding cancer progression, PDIA3 and PDIA6 gene expression are established markers of aggressiveness in primary ductal breast cancer." (PMID 29262583, 2017). "Comparison of these selective PDIA1 inhibitors with E64FC26; a potent pan‐style inhibitor which inhibits; PDIA1, PDIA3, PDIA4, PDIA6 and TXNDC5, would give an indication as to whether inhibition of PDIA1 alone is sufficient for suppressing cancer cell growth." (PMID 33742523, 2021).
cancer (continued). "Compared with the adjacent noncancerous tissues, the expression of PDIA6 was significantly elevated in cancer tissues at both mRNA and protein levels, as detected by qPCR and western blotting." (PMID 33761940, 2021).
infection (3 papers, 2015 to 2022). The state of being infected such as from the introduction of a foreign agent such as serum, vaccine, antigenic substance or organism. "In response to infection, in male mice, the TACC2, BUB1B, ATP5MC3, and MYO1E, and in female mice, the CAP1, MRPL2, COX5A, KLHL21, PDIA6, TSPO, and USP14 had direct interaction with TP-53." (PMID 35844510, 2022). "PDIA6 expression was significantly increased following cell infection with OE-PDIA6 in SCC9 and Cal27 cells, while PDIA6 level was decreased when cells were transfected with si-PDIA6 at mRNA and protein levels." (PMID 33761940, 2021).
hematologic malignancies (1 paper, 2022). "The same study also showed that PDIA6 can also elicit a similar antibody response, suggesting the therapeutic potential of PDIA1 and PDIA6 in hematologic malignancies." (PMID 35965326, 2022).
PDIA6 also shares sentences with these, for which no sentence is quoted: Hodgkins lymphoma (3 papers); cervical cancer (2); chronic lymphocytic leukemia (2); invasive ductal carcinomas (2); multiple myeloma (2); Alzheimer disease (1); bladder tumor (1); brain cancer (1); head and neck cancer (1); invasive lobular carcinoma (1); liver cancer (1); lobular carcinomas (1); lymphoma (1); microcephaly (1); Obesity (1); polycystic kidney disease (1); thrombotic disease (1).